PIWIL1 (piwi like RNA-mediated gene silencing 1)
Description:
Endoribonuclease that plays a central role in postnatal germ cells by repressing transposable elements and preventing their mobilization, which is essential for the germline integrity. Acts via the piRNA metabolic process, which mediates the repression of transposable elements during meiosis by forming complexes composed of piRNAs and Piwi proteins and governs the methylation and subsequent repression of transposons. Directly binds methylated piRNAs, a class of 24 to 30 nucleotide RNAs that are generated by a Dicer-independent mechanism and are primarily derived from transposons and other repeated sequence elements. Strongly prefers a uridine in the first position of their guide (g1U preference, also named 1U-bias). Not involved in the piRNA amplification loop, also named ping-pong amplification cycle. Acts as an endoribonuclease that cleaves transposon messenger RNAs. Besides their function in transposable elements repression, piRNAs are probably involved in other processes during meiosis such as translation regulation. Probable component of some RISC complex, which mediates RNA cleavage and translational silencing. Also plays a role in the formation of chromatoid bodies and is required for some miRNAs stability. Required to sequester RNF8 in the cytoplasm until late spermatogenesis; RNF8 being released upon ubiquitination and degradation of PIWIL1. [Isoform 3]: May be a negative developmental regulator.
Synonyms: HIWI; PIWI; CT80.1; MIWI
Tractability: PROTAC: UniProt records ubiquitination sites on it; ubiquitination databases record sites on it.
Gene: Protein-coding gene on chromosome 12 (130,337,887 to 130,372,637, forward strand). Ensembl gene ENSG00000125207.
Subcellular location: Cytoplasm
Pathways (Reactome):
Gene expression (Transcription): PIWI-interacting RNA (piRNA) biogenesis
Gene Ontology:
Molecular function: piRNA binding; protein binding; mRNA binding; RNA endonuclease activity; mRNA cap binding complex binding; nucleic acid binding; protein kinase binding; RNA binding; single-stranded RNA binding
Biological process: spermatid development; piRNA processing; primary piRNA processing; regulatory ncRNA-mediated gene silencing; sperm DNA condensation; spermatogenesis; transposable element silencing by piRNA-mediated heterochromatin formation; piRNA-mediated gene silencing by mRNA destabilization
Cellular component: chromatoid body; cytoplasm; P granule; dense body; nucleus
Genetic constraint (gnomAD): Loss-of-function variants: 55 observed, 87.42 expected, observed/expected ratio (o/e) 0.63, 90% interval 0.51 to 0.79. The upper end of that interval is the gene's LOEUF score, 0.79, which puts it in group 3 of 6, group 1 being the genes least tolerant of losing a copy. Missense variants: 604 observed, 956.84 expected, observed/expected ratio (o/e) 0.63, 90% interval 0.59 to 0.68. Synonymous variants: 320 observed, 333.09 expected, observed/expected ratio (o/e) 0.96, 90% interval 0.88 to 1.05.
Homologues: Orthologues: chimpanzee PIWIL1 (99% identical), macaque PIWIL1 (99% identical), pig PIWIL1 (96% identical), rabbit PIWIL1 (95% identical), mouse Piwil1 (95% identical), rat Piwil1 (95% identical), guinea pig PIWIL1 (92% identical), dog PIWIL1 (87% identical), tropical clawed frog piwil3 (72% identical), tropical clawed frog piwil3 (70% identical), zebrafish piwil1 (65% identical), Drosophila melanogaster aub (37% identical), and 2 more. Paralogues in human: PIWIL3 (50% identical), PIWIL4 (50% identical), PIWIL2 (40% identical).
Diseases named in the same sentence as PIWIL1 in open-access papers:
PIWIL1 is named in the same sentence as 90 diseases in open-access papers, as found by Europe PMC text mining. Sharing a sentence is not in itself a finding about the gene and the disease. The quoted sentences say what the papers report.
gastric cancer (30 papers, 2009 to 2026). A primary or metastatic malignant neoplasm involving the stomach. "Knockout of PIWIL1 in gastric cancer cells is associated with increased migration, invasion, and metastasis, both in vitro and in vivo." (PMID 39596284, 2024). "Studies in gliomas, endometrial, pancreatic and gastric cancer have also shown an association of higher levels of PIWIL1 with more aggressive disease." (PMID 38303021, 2024). "For example, PIWIL1 expression is progressively increased in normal gastric tissues, atrophic gastritis, intestinal metaplasia and gastric cancer tissues, holding diagnostic potentials for improving early gastric cancer detection." (PMID 33718392, 2021). "The PIWIL1 gene is located closed to the extreme of the long arm of chromosome 12q24.33, and its expression was associated to gastric cancer and precancerous development with an expression pattern similar to Ki67." (PMID 31443431, 2019). "Previous studies demonstrate that high levels of Piwil1 expression could increase the risk for tumor-related death and may be a poor prognostic factor for esophageal squamous cell carcinoma, gastric cancer and hepatocellular carcinoma." (PMID 26506848, 2015). "Research indicates that PIWIL1 is significantly expressed in tissues and cell lines of gastric cancer." (PMID 40296904, 2025). "Another study in gastric cancer showed high PIWIL1 expression in gastric cancer tissues, with its knockout significantly reducing cell proliferation, migration, metastasis, and tumorigenesis." (PMID 39358554, 2024). "Ectopic expression of PIWIL1 has been described in many tumor types such as colorectal carcinoma, pancreatic cancer, gliomas, gastric cancer and endometrial cancer." (PMID 38303021, 2024). "In a piRNA-independent manner, PIWIL1 was also shown to interact with various components of the nonsense-mediated mRNA decay machinery such as UPF1 in gastric cancer." (PMID 38303021, 2024). "PIWIL1 Knocking out the PIWIL1 gene (PIWIL1-KO) has significantly reduced gastric cancer cell proliferation, migration, metastasis, and tumorigenesis." (PMID 38012622, 2023). "Betulinic acid, a plant secondary metabolite isolated from birch trees, was shown to inhibit cell proliferation and reduce the levels of PIWIL1 in gastric cancer and lung cancer." (PMID 33718392, 2021). "The expression levels of PIWIL1 were significantly increased in esophageal cancer, gastric cancer, head and neck cancer, kidney cancer, pancreatic cancer, and prostate cancer tissues compared with respective normal tissues." (PMID 33718392, 2021). "Knockout of PIWIL1 using the CRISPR/Cas9 system markedly attenuates the tumor growth of gastric cancer in vivo." (PMID 33718392, 2021). "Piwil1 has been found to be frequently overexpressed in various tumor types, including gastric cancer, breast cancer and endometrial cancer." (PMID 26506848, 2015). "Piwi protein expression profiles have recently received much attention for their potential functional involvement in oncogenesis in a variety of human cancers and Piwil1 and Piwil 2 have been shown to be independent prognostic factors in gastric cancer." (PMID 25007054, 2014). "PIWIL1 has been identified as a potential target for the precision treatment of gastric cancer." (PMID 40296904, 2025). "PIWIL1 may, as an oncogene, be overexpressed in multiple types of tumors, such as gastric cancer, lung cancer, hepatocellular carcinoma, pancreatic adenocarcinoma, and endometrial cancer." (PMID 38012622, 2023). "Furthermore, a piRNA-independent mechanism has been proposed to account for the oncogenic functions of PIWIL1 in gastric cancer cells." (PMID 33718392, 2021). "While a single-nucleotide polymorphisms study (SNPs) has shown that the GG genotype and G allele of rs28416520 within the PIWIL1 gene promoter CpG 67 region are associated with an increased risk of gastric cancer, the impact of SNPs of PIWIL1 gene on EOC risk has not been studied." (PMID 38012622, 2023).
gastric cancer (continued). "However, recent observations that PIWIL1 does not associate with piRNAs in pancreatic and gastric cancer cells supported the hypothesis that upregulated PIWIL1 protein probably functions in a piRNA-independent manner in cancer cells." (PMID 33718392, 2021). "In addition, PIWIL1 has been described to exhibit a poor prognostic value in soft-tissue sarcoma, esophageal squamous cell carcinoma, colorectal cancer, gliomas, human hepatocellular carcinoma, gastric cancer, lung cancer, gynecological cancers, renal cell carcinoma, and non-small cell lung cancer." (PMID 31443431, 2019). "Gastric cancers overexpress piR-651, promoting G2/M arrest evasion; lung cancers feature PMLCPIR enhancing ITGB1-PI3K-AKT signaling; multiple myeloma leverages piR-823 for proliferation; and hepatocellular carcinoma shows PIWIL1 upregulation tied to stemness." (PMID 42022287, 2026). "Although the oncogenic function of Piwil1 in gastric cancer cells was reported to be independent of its partner piRNAs, Piwi proteins have showed significant synergy with related piRNAs in regulating human cancer." (PMID 34295823, 2021). "The expression of the 5 other genes were found to be repressed by over-expressed non-coding RNA or by aberrant methylation of the promoter: GALNT5 in gastric cancer, ADAM6 in lung adenocarcinoma, PIWIL1 and PIWIL4 in lung adenocarcinoma and renal cell carcinoma." (PMID 31568528, 2019). "Although the prognostic significance of PIWIL1 expression has not previously been examined in NSCLC, it has been associated with poor outcome in other tumors, including glioma, pancreatic cancer, colorectal cancer, esophageal cancer, liver cancer, gastric cancer, and sarcomas." (PMID 25742785, 2015).
lung carcinoma (26 papers, 2012 to 2026). "Other studies indicated that the suppression of PIWIL1 expression via plasmids containing short hairpin RNA (shRNAs) was associated with a decrease in the cell proliferation and inducing apoptosis of lung cancer stem cells." (PMID 31890151, 2019). "PIWIL1 knockdown in lung cancer cells inhibits proliferation, promotes apoptosis, and reduces the number of ALDH-1-positive cells." (PMID 39596284, 2024). "Increasing evidence indicates that PIWIL1 is frequently expressed in diverse cancer types, including lung cancer, hinting at its potential oncogenic roles in cancer development or progression." (PMID 39560475, 2024). "Knockdown of RASSF1 and PIWIL1 increased the expression of GMIP (a hypermethylated gene), which, in turn, caused the proliferation and migration of lung cancer cells." (PMID 36915129, 2023). "Further, we found that treatment of wildtype lung cancer cells or lung cancer cells overexpressing RASSF1C or PIWIL1 with piR-35127 and 46545 (both down-regulated by RASSF1C) decreased lung cancer cell invasion/migration." (PMID 36826019, 2023). "We also report that piR-46546 and piR-35137 attenuate invasion/migration of lung cancer cells overexpressing RASSF1C or PIWIL1 in vitro." (PMID 36826019, 2023). "Treatment of wildtype lung cancer cells or cells overexpressing RASSF1C or PIWIL1 with piR-35127 and piR-46545 decreased cell migration/invasion." (PMID 36826019, 2023). "It has been reported that PIWIL1 promotes lung cancer cell proliferation, migration, and invasion; and PIWIL1 knockdown in LCSCs resulted in growth inhibition both in vitro and in vivo in a nude mouse model." (PMID 33227088, 2020). "To increase our understanding of the impact of the RASSF1C-PIWIL1-piRNA pathway on lung cancer, in this study we assessed the impact of the over-expressing RASSF1C and knocking down of RASSF1C and PIWIL1 genes on lung cancer cell gene methylation." (PMID 33227088, 2020). "RASSF1C promotes EMT of lung cancer cells, and others have shown the PIWIL1 induces EMT of endometrial cells to promote metastasis." (PMID 33227088, 2020). "In this study, we observed that PIWIL1 was aberrantly expressed in lung cancer tissues and induced the malignant phenotype." (PMID 29168346, 2018). "In previously published work, we have identified that Dorsomorphin (AMPK inhibitor) up-regulates and Trichostatin A (HDAC inhibitor and AMPK activator) down-regulates RASSF1C and PIWIL1 mRNA levels in lung cancer cells." (PMID 28423657, 2017). "In a previous study, the same group showed that PIWIL1 gene silencing decreased proliferation and promoted apoptosis in lung cancer stem cells." (PMID 25742785, 2015). "This is further supported by slowed tumor growth after knockdown of PIWIL1 in lung cancer cell lines." (PMID 24932571, 2014). "PIWIL1 protein levels were also reduced in lung cancer cells co-expressing RASSF1C-IGFBP-5 compared to cells over-expressing RASSF1C." (PMID 25007054, 2014). "Taken together, our findings provide significant data to propose a model for investigating the role of RASSF1C/PIWIL1 proteins in initiation and progression of lung cancer." (PMID 22591718, 2012). "We are interested in pursuing studies to determine the mechanism(s) through which RASSF1C modulates PIWIL1 gene expression and its impact on lung cancer cell growth." (PMID 22591718, 2012). "We then further validated the up-regulation of PIWIL1 gene expression in lung cancer cells over-expressing RASSF1C using immunostaining and Western blot analysis." (PMID 22591718, 2012). "We investigated the expression levels of PIWIL1 in lung cancer cell lines and found the PIWIL1 expression is indeed elevated in lung cancer cell lines compared to normal lung epithelial cells." (PMID 22591718, 2012).
lung carcinoma (continued). "We have previously shown that RASSF1C induces expression of PIWIL1 and accumulation of β-catenin (both associated with stem cell self-renewal) and regulates expression of PIWI-interacting RNAs (piRNAs) associated with stem cell function in lung cancer cells." (PMID 36826019, 2023). "We have shown that RASSF1C induces expression of PIWIL1 and accumulation of β-catenin (both associated with stem cell self-renewal) and regulates expression of PIWI-interacting RNAs (piRNAs) associated with stem cell function in lung cancer cells." (PMID 36826019, 2023). "In this regard, we report that RASSF1C and PIWIL1 may promote lung cancer cell metastasis through modulation of tumor microenvironment/ECM through regulation of Collagen I, P4HA2, and PLOD2 gene expression." (PMID 36826019, 2023). "In support of this idea, we found that overexpression of PIWIL1 promotes lung cancer cell migration/invasion, which is consistent with published reports; and cells overexpressing PIWIL1 display increased protein levels of P4HA2, PLOD2, and collagen I to some extent." (PMID 36826019, 2023). "In addition, PIWIL1 is essential for stem cell maintenance and the self-renewal of germ stem cells, hematopoietic stem cells, mesenchymal stem cells, and lung cancer stem cells (CSCs)." (PMID 35083142, 2021). "In addition, aberrant promoter DNA hypomethylation is one of the major mechanisms for PIWIL1 overexpression in lung cancer and endometrial cancer." (PMID 33718392, 2021). "This provides further support for the hypothesis that GMIP could be regulated by a PIWIL1-piRNA complex in lung cancer cells." (PMID 33227088, 2020). "Moreover, PIWIL1 is considered a potential target for treatment design in glioblastoma, hepatocellular carcinoma, and lung cancer." (PMID 31443431, 2019). "Our previous work suggests that RASSF1C may promote lung cancer stem cell development and progression, in part, through modulation of a novel PIWIL1-piRNA pathway." (PMID 30719208, 2019). "Also, it demonstrated that the PIWIL1 had the high expression in lung cancer cell lines compared with normal cells." (PMID 31890151, 2019). "Thus, in this study, we aimed to examine the expression pattern of PIWIL1, and further characterized the biological function and potential regulatory mechanism of PIWIL1 in lung cancer." (PMID 29168346, 2018). "We observed that PIWIL1 was expressed in testis and lung adenocarcinoma but not in other normal tissues, and its high expression was associated with shortened survival of lung cancer patients." (PMID 29168346, 2018). "We also show that IGFBP-5 may be an important molecule for modulating RASSF1C/PIWIL1 effects in lung cancer." (PMID 25007054, 2014). "Therefore, we wanted to study the effect of RASSF1C/IGFBP-5 interaction on PIWIL1 gene expression in lung cancer cells." (PMID 25007054, 2014). "All of this suggests that RASSF1C may enhance lung cancer stem cell proliferation, and it is possible that this happens through up-regulation of PIWIL1 gene, a stem cell self-renewal gene." (PMID 25007054, 2014). "The IGFBP-5, RASSF1C, and PIWIL1 genes may constitute a new axis in controlling lung cancer cell development and progression." (PMID 25007054, 2014). "Thus, we wanted to investigate the effect of RASSF1C/ IGFBP-5 interaction on PIWIL1 gene expression in lung cancer cells." (PMID 25007054, 2014). "In this study we also found that PIWIL1 gene expression is significantly elevated in lung cancer cell lines compared to normal lung epithelial cells underscoring a potential role for PIWIL1 in lung cancer proliferation and progression." (PMID 22591718, 2012). "To further investigate if RASSF1C actions are mediated by the MEK-ERK1/2 pathway, we treated the cells with the MEK-ERK inhibitor CI-1040 and interestingly found that reduction of the ERK1/2 phosphorylation resulted in the down-regulation of PIWIL1 mRNA levels in lung cancer cells." (PMID 22591718, 2012).